THOC1 (THO complex subunit 1)
Diseases named in the same sentence as THOC1 in open-access papers:
THOC1 is named in the same sentence as 28 diseases in open-access papers, as found by Europe PMC text mining. Sharing a sentence is not in itself a finding about the gene and the disease. The quoted sentences say what the papers report.
breast carcinoma (9 papers, 2009 to 2026). "In breast cancer, THOC1 expression was elevated compared with normal epithelium, and elevated levels correlate positively with tumor size and metastatic progression." (PMID 41496272, 2026). "THOC1 expression is elevated in breast cancer than in normal epithelia, and its expression level is positively correlated with tumor size and metastasis." (PMID 32669125, 2020). "It has been described that THOC1 is overexpressed in breast cancer; however, we only detected 3 out of 10 tumor samples with mRNA levels higher than the corresponding normal samples." (PMID 21329510, 2011). "Increased expression of this complex (Thoc1) in breast cancer correlates with tumor size and the metastatic state of the tumor progression, thus suggesting that modulation of the TREX-complex could also have a role in pancreatic cancer." (PMID 22078386, 2011). "This study shows that not only the expression of THOC1, but also that of THO/TREX complex is upregulated in breast cancer cells." (PMID 21329510, 2011). "We evaluated the expression of the components of the human THO complex, THOC1, THOC2, THOC3, THOC5, THOC6 and THOC7, as well as the expression levels of UAP56 and ALY in breast cancer cell lines." (PMID 21329510, 2011).
hepatocellular carcinoma (6 papers, 2020 to 2024). A malignant tumor that arises from hepatocytes. "Previous research has shown that the ribonucleoprotein encoded by THOC1 plays a crucial role in regulating the balance of myeloid progenitor cell proliferation and apoptosis in adult mice, and THOC1 deficiency also inhibits the proliferation of hepatocellular carcinoma cells." (PMID 39044280, 2024). "The clinical data analysis of liver hepatocellular carcinoma samples downloaded from The Cancer Genome Atlas reveals that the THO Complex 1 (THOC1) is remarkable upregulated in HCC and associated with poor prognosis." (PMID 32669125, 2020). "For example, knockdown of THOC1 enhances sensitivity to cisplatin by increasing R‐loop formation in hepatocellular carcinoma." (PMID 36054300, 2022). "THOC1 also inhibits the proliferation of tumor cells in hepatocellular carcinoma and prostate cancer." (PMID 35126467, 2021). "The common flavonoid luteolin reduces hepatocellular carcinoma cell proliferation in mice and increases cisplatin sensitivity through THOC1 inhibition." (PMID 34359660, 2021). "Recent studies show that the knockdown of THOC1 reduces the proliferation of hepatocellular carcinoma, and THOC1 is essential for mouse development, THOC1 may be the candidate gene for larger liver." (PMID 39058882, 2024). "Finally, a recent study showed that THOC1 depletion in hepatocellular carcinoma cells induces R-loop accumulation and increases sensitivity to cisplatin." (PMID 34359660, 2021).
lung carcinoma (6 papers, 2011 to 2021). "Recent research found that high levels of THOC1 were associated with tumor size and aggressiveness in breast and lung cancer cells, and that down-regulation of THOC1 was essential for the NO-mediated cytotoxicity induced by CCL-34 in cancer cells." (PMID 32518584, 2020). "High levels of hHPR1/THOC1 have been observed in breast and lung cancer cells and are associated with tumor size and aggressiveness." (PMID 21329510, 2011). "High levels of the THOC1 protein were observed in the nuclei of ovarian, and lung cancer tumors in comparison with normal tissues." (PMID 21329510, 2011). "It is found that 3 of the 10 SFs are reported to be connected with lung cancer, namely LSM7, C1QBP, and THOC1." (PMID 35126467, 2021).
breast tumors (3 papers, 2008 to 2012). "Overexpression of THOC1 has previously been correlated to the grade of invasiveness in breast tumor, and also a relationship between the levels of this protein in non-small lung cancers has been suggested." (PMID 21329510, 2011).
prostate carcinoma (3 papers, 2020 to 2021). A carcinoma that arises from epithelial cells of the prostate gland. "THOC1 has previously been associated to prostate cancer aggressiveness." (PMID 34572914, 2021). "THOC1, THOC2, THOC5 and THOC6, members of the THO subcomplex of TREX which participates in mRNA processing and transport of RNPs from nucleus to cytoplasm, are present in HMGB1 immunoprecipitates from ovary and prostate cancer cells." (PMID 34572914, 2021).
deafness (2 papers, 2020 to 2024). An inherited or acquired condition characterized by the complete loss of the ability to hear from one or both ears. "The new clinical symptoms in our case were unilateral deafness and hepatomegaly, deletion completely covered THOC1 gene [OMIM: 606930], and THOC1 mutation causes deafness, autosomal dominant 86 (type 86) [OMIM: 620280]." (PMID 39058882, 2024). "Surprisingly, though hair cell apoptosis is a key step towards progressive and age-related hearing loss, THOC1 represents only one of a very few deafness-causing genes directly involved in this process." (PMID 32776944, 2020). "The ClinGen Database Haplodose Insufficiency (HI) prediction tool determined that HI, THOC1 HI may cause unilateral deafness." (PMID 39058882, 2024). "Therefore, this study provides a new THOC1 deletion associated with unilateral deafness." (PMID 39058882, 2024). "Therefore, we determined that insufficient haploids of THOC1 caused unilateral deafness." (PMID 39058882, 2024). "Therefore, we hypothesized that the deletion of the THOC1 gene resulted in a haplodose of inadequate haplodose of modified gene expression, which ultimately led to unilateral deafness." (PMID 39058882, 2024). "However, it has not been reported whether deletion of the THOC1 gene causes deafness." (PMID 39058882, 2024).
glioblastoma (2 papers, 2019 to 2026). The most malignant astrocytic tumor (WHO grade IV). "Despite this emerging evidence across tumor types, the role of THOC1 in glioblastoma remains poorly defined." (PMID 41496272, 2026). "THOC1 overexpression also led to tumorigenic properties in neural stem cells, which are related to glioblastoma." (PMID 41496272, 2026). "While our data show that the interaction of THOC1 and SIN3A regulates R-loops globally, the impact on glioblastoma may be disproportionately driven by its impact on telomeres." (PMID 41496272, 2026).
hearing loss (2 papers, 2020 to 2023). "To elucidate the role of THOC1 in the inner ear, we generated a series of Thoc1 mutant zebrafish that mimicked the human hearing impairment by losing the C-startle response." (PMID 32776944, 2020).
ovarian tumors (2 papers, 2011 to 2012). "In contrast to the atlas IHC data, we observe THOC1 overexpression in ovarian tumors and a decrease in THOC1 expression in testis and skin tumor tissues." (PMID 21329510, 2011). "Our results suggest that THOC1 could be relevant in ovarian tumors, in which THOC1 expression levels were high in almost all the carcinomas analyzed." (PMID 21329510, 2011).
colorectal cancer (1 paper, 2026). A primary or metastatic malignant neoplasm that affects the colon or rectum. "THOC1 is elevated in various cancers including breast, hepatocellular, and colorectal cancer where it appears to be essential for sustaining neoplastic transformation, as tumor cells depend on its function to maintain malignant growth." (PMID 41496272, 2026).
gastric cancer (1 paper, 2021). A primary or metastatic malignant neoplasm involving the stomach. "Effective blockade of STAT3 activity by the STAT3 inhibitor stattic sensitized gastric cancer cells to cisplatin and reduced expression of the cisplatin resistance‐related genes G3BP2, THOC1, ATP7A, and OTUD1." (PMID 34375503, 2021). "Effective blockade of the STAT3 activity by STAT3 inhibitor sensitized gastric cancer cells to cisplatin and reduced the cisplatin‐resistant‐related gene G3BP2, THOC1, ATP7A, and OTUD1 expression." (PMID 34375503, 2021).
glioma (1 paper, 2026). A benign or malignant brain and spinal cord tumor that arises from glial cells (astrocytes, oligodendrocytes, ependymal cells). "Future studies in glioma-prone cells will further clarify the role of THOC1 in promoting tumorigenesis." (PMID 41496272, 2026). "In contrast, THOC1 has not been previously implicated in GBM and showed consistent dropout across guides, suggesting a novel role in maintaining glioma cell viability." (PMID 41496272, 2026).
skin cancer (1 paper, 2011). "A loss of THOC1 protein staining was observed in testis and skin cancers, in up to 75% of the samples." (PMID 21329510, 2011).
skin tumor (1 paper, 2011). "In addition, a statistically significant reduction of THOC1 transcripts was observed in thyroid, testis and skin tumors, even though in the later the differences were lower." (PMID 21329510, 2011).
cancer (18 papers, 2010 to 2026). A tumor composed of atypical neoplastic, often pleomorphic cells that invade other tissues. "Previous studies have shown that loss of THOC1 impairs mRNA export and that THOC1 levels are elevated in several cancers, including prostate, ovarian, and colorectal." (PMID 41496272, 2026). "As a reduction of THOC1 was also associated with some cancers such as those of skin and testis, these results argue against the idea that THOC1 expression would be required for proliferation and survival of oncogene-transformed cells." (PMID 21329510, 2011). "In our study, the knockdown of THOC1 activity is expected to inhibite the viability of cancer cells." (PMID 32669125, 2020). "Human cancer cell lines with THOC1 depletion show increased sensitivity to camptothecin and cisplatin." (PMID 32669125, 2020). "Increasing evidence demonstrates that THOC1 expression is elevated in many human cancers, such as prostate, colorectal and lung cancers, and associated with poor prognosis." (PMID 32669125, 2020). "Multiple TREX mRNA export complex subunits (e.g., THOC1, THOC2, THOC5, THOC6, THOC7) have now been implicated in neurodevelopmental disorders (NDDs), neurodegeneration and cancer." (PMID 32116545, 2020). "Taken together, these data suggest that BUB1, STAG2, SMC3, and THOC1 function in cell growth, proliferation, and tumorigenesis and thus play crucial roles in cancer development." (PMID 32518584, 2020). "The TREX subunit Thoc5 is the target of leukaemogenic tyrosine kinases and two other TREX subunits, Thoc1 (Hpr1) and Alyref, are dysregulated in cancer cells." (PMID 25662211, 2015). "Given the link between genome instability and cancer, we have performed a comparative analysis of the expression patterns of THOC1, a THO complex subunit, and ALY in tumor samples." (PMID 21329510, 2011). "Cancer cells require higher levels of THOC1 for survival than normal cells." (PMID 32669125, 2020). "THOC1 may represent a novel and effective molecular target for cancer therapy." (PMID 32669125, 2020). "The deletion of THOC1 also causes apoptosis in cancer cells, but not in normal fibroblasts." (PMID 20051105, 2010). "First the mRNA levels of THOC1 and ALY in tumor tissues by hybridization of a Cancer Profiling Array II (Clontech) were evaluated." (PMID 21329510, 2011). "In contrast to THOC1, ALY protein is highly detected in normal proliferative cells, but poorly in high-grade cancers." (PMID 21329510, 2011). "On the other hand, Thoc1 is overexpressed in a variety of cancers, and depletion of Thoc1 in those cancer cells, but not in normal cells, induce apoptotic cell death." (PMID 32776944, 2020). "The up-regulation of THOC1 and THO complex expression, readily seen in a range of cancer types, may correlate with tumor size and have a greater effect in hormone-dysregulated cancers." (PMID 27679854, 2016). "The marked reduction in metastatic capacity and cancer cell proliferation following ALYREF, THOC1 and LUZP4 depletion further suggests that there may be therapeutic benefit in targeting TREX." (PMID 27679854, 2016).
tumor (14 papers, 2011 to 2026). "Post-mortem analysis confirmed THOC1 knockdown via IHC, and H&E staining showed that tumor size was reduced in mice implanted with THOC1-knockdown GBM43 cells." (PMID 41496272, 2026). "Inhibiting THOC1 increases genotoxic R-loop accumulation, reducing tumor burden and extending survival in vivo." (PMID 41496272, 2026). "In vivo studies using a GBM43 PDX model revealed that mice implanted with THOC1-knockdown cells had a significantly increased median survival and reduced tumor size, emphasizing THOC1′s role in tumor growth and aggressiveness." (PMID 41496272, 2026). "Single-cell RNA sequencing from GBMSeq showed that THOC1 expression is highly localized to the tumor core and elevated in contrast-enhancing regions relative to non-enhancing areas." (PMID 41496272, 2026). "H1B.F3 cells with control or THOC1-overexpression lentiviral vectors were injected into mice, which were monitored for tumor development and survival." (PMID 41496272, 2026). "THOC1 mRNA expression – obtained from GlioVis portal patient data – was elevated in GBM samples compared to non-tumor tissue across multiple datasets." (PMID 41496272, 2026). "Tumor proliferation of THOC1-overexpression cells was measured via MTT assays and cell cycle flow cytometry." (PMID 41496272, 2026). "The IHC analysis of PCNA and Ki67 also indicated that the proliferative capacity of tumor was inhibited after luteolin treatment or THOC1 knockdown." (PMID 32669125, 2020). "As a result, the PLC/PRF/5 cells with THOC1 knockdown exhibited reduced tumor size than their control counterparts (P < 0.05)." (PMID 32669125, 2020). "The correlation analysis of THOC1 and proliferation markers PCNA (P < 0.001, r = 0.56) and Ki67 (P < 0.001, r = 0.53) revealed that the expression of THOC1 was positively related to tumor proliferation." (PMID 32669125, 2020). "Overall, these data demonstrated that THOC1 can enhance tumorigenesis in vivo by increasing tumor cell proliferation." (PMID 32669125, 2020). "This links THOC1 with tumor survival as mRNP biogenesis cannot occur efficiently enough to maintain rapid cell division in its absence." (PMID 27679854, 2016). "On the other hand, overexpression of human Yra1 and Hpr1 orthologues ALY and THOC1, respectively, in a broad range of tumors, highlights the ability of these proteins to undergo stoichiometry changes in tumor cells." (PMID 27035147, 2016). "The increase in the expression of THOC1 protein has been confirmed by western blot in some ovarian and lung normal and tumor samples." (PMID 21329510, 2011). "The GeneCard data show changes in THOC1 mRNA levels in tumor versus normal tissues, in almost all samples analyzed: higher levels in lymphoid node, breast, lung, colon, liver, pancreas, prostate and skin and lower in thyroid, cortex and cerebellum." (PMID 21329510, 2011). "A weak signal for THOC1 protein was detected in the cytoplasm of normal ductal epithelial cells and a strong nuclear signal in 80% of the tumor samples analyzed." (PMID 21329510, 2011). "Conversely, overexpressing THOC1 in non-cancerous neural stem cells bolstered transformation capacity, decreasing survival and causing tumor engraftment in vivo (p<0.01)." (PMID 41496272, 2026). "In addition, in vivo data demonstrate that THOC1 can enhance tumorigenesis by increasing tumor cell proliferation." (PMID 32669125, 2020). "Furthermore, the inhibition of THOC1 activity by luteolin enhances the chemosensitivity of HCC tumor cells to cisplatin." (PMID 32669125, 2020). "Furthermore, the inhibition of THOC1 activity by luteolin has enhanced the chemosensitivity of HCC tumor cells to cisplatin." (PMID 32669125, 2020). "Consequently, the HepG2 cells with THOC1 overexpression displayed greater tumor mass than their control counterparts (P < 0.05)." (PMID 32669125, 2020).
tumor (continued). "The array contained a representation of tumor specimens of those organs in which, according to the results of the analysis of the cDNA tumor array, THOC1 and ALY could be expected to be deregulated." (PMID 21329510, 2011). "In addition, THOC1 is required for tumor cells that undergo neoplastic transformation." (PMID 32669125, 2020). "Our experimental results showed that after THOC1 is disrupted, the growth of T-ALL tumor cells significantly slows, apoptosis increases, and the cleavage of the apoptotic molecule PARP significantly increases." (PMID 39044280, 2024). "Among which, SLC25A15, RAD9A, PRF19, THOC1, and TIPIN were significantly overexpressed in tumor tissues in both the TCGA and our local cohorts." (PMID 36033441, 2022). "Next, we decided to extend the comparative analysis between THOC1 and ALY, with the analysis by immunostaining of the protein levels and distribution of these factors in tumor samples." (PMID 21329510, 2011). "We show that the expression of two mRNP factors, THOC1 and ALY are altered in several tumor tissues." (PMID 21329510, 2011). "The study was extended by performing immunostaining analysis of THOC1 and ALY in normal and tumor breast tissues in order to see if the protein levels of these factors had also increased." (PMID 21329510, 2011). "From the analyses of cDNA arrays we can conclude that there is a differential pattern of expression of THOC1 and ALY in tumor tissues." (PMID 21329510, 2011). "At the same time, the different expression pattern of THOC1, as representative of THO, and ALY in normal and tumor tissues, indicates a different relevance of these factors in the tumorogenisis process." (PMID 21329510, 2011). "The results showed that both the expression of THOC1 and ALY is altered in several tumor tissues, suggesting a connection of these mRNP biogenesis factors with tumorogenesis." (PMID 21329510, 2011). "Importantly, expression of ALY and other related mRNP factors such as human THOC1/hHpr1, URH49, and CIP29/hTho1 is deregulated in tumor cells, suggesting a possible connection between mRNP metabolism and tumorigenesis." (PMID 27035147, 2016). "Moreover, in vivo experiments demonstrated that THOC1-overexpressing non-cancerous cells were capable of inducing tumor engraftment in mice, indicating the oncogenic potential of THOC1 and its role in transforming normal cells into a cancerous phenotype." (PMID 41496272, 2026).
infection (1 paper, 2022). The state of being infected such as from the introduction of a foreign agent such as serum, vaccine, antigenic substance or organism. "Co-immunoprecipitation experiments revealed the formation of DDX39B/THOC1/THOC4/CIP29/NP complexes during infection; as found earlier, RNase A treatment resulted in the loss of NP from the complex." (PMID 36084138, 2022).
THOC1 also shares sentences with these, for which no sentence is quoted: ovarian carcinoma (2 papers); age-related hearing loss (1); B cell lymphoma (1); craniofacial microsomia (1); Hearing impairment (1); invasive breast ductal carcinoma (1); melanoma (1); mental disorder (1); neurodevelopmental disorder (1); pancreatic cancer (1); retinitis pigmentosa (1).